FOXD1 (forkhead box D1)
Diseases named in the same sentence as FOXD1 in open-access papers (continued):
Sharing a sentence is not in itself a finding about the gene and the disease.
tumor (continued). "Forkhead Box D1 (FOXD1) plays an oncogene role in various tumor types." (PMID 34028536, 2021). "The finding that FOXD1 expression is mosaic in the majority of tumors indicates that it may be activated or inactivated in subpopulations of tumor cells." (PMID 33761914, 2021). "However, FOXD1 function in the development of tumor biology and related molecular mechanism is still in preliminary exploration stage." (PMID 34772357, 2021). "Moreover, the positive correlation between FOXD1 expression and immunosuppressive genes, such as PD-L1, IL-10, TGFB1 and TGFBR1, indicate the key role of FOXD1 in regulating tumor immunology." (PMID 34028536, 2021). "To understand if this mechanism could underlie the reduced patient survival seen in ccRCC cases with high FOXD1 tumor expression, we performed a correlation analysis between FOXD1 expression in ccRCC tumors and biological pathways." (PMID 33761914, 2021). "We and others have shown that FOXD1 or Gal-3 are increased in advanced tumor tissues." (PMID 31795213, 2019). "In conclusion, our study revealed that CXCL5 promotes tumor angiogenesis by controlling FOXD1 expression and transcriptional activity through the activation of the AKT/NF-κB pathway, suggesting that CXCL5 is a significant predictor in tumorigenesis and progression." (PMID 30792394, 2019). "Given the relationship between FOXD1 and Gal-3, it is most likely that targeting both FOXD1 and Gal-3 may have greater effects on tumor progression that targeting either protein alone." (PMID 31795213, 2019). "Moreover, the combined knockdown of UBA2, RALY, and FOXD1 resulted in the smallest tumor volume." (PMID 37906341, 2023). "Similarly, tumor growth rate and tumor volume were reduced in mice bearing FOXD1-knockdown cells." (PMID 36229838, 2022). "Based on previous work demonstrating a role for FOXD1 in controlling expression of MICU1, which regulates calcium flux in the mitochondrion, we hypothesized that reduced proliferative capacity of FOXD1 null tumor cells may be due to reduced energy production capacity." (PMID 33761914, 2021). "Numerous studies thus far have shown that FOXD1 as a key role in the occurrence, development and malignant regulation of multitudinous human malignance and its abnormal up-regulation was obviously related to cell proliferation, tumor metastasis and invasion as well as poor prognosis." (PMID 34772357, 2021). "However, the function of FOXD1 in tumor angiogenesis is poorly understood." (PMID 30792394, 2019). "Therefore, expression in blastemal-predominant tumours would be expected to be higher than in triphasic or epithelial-predominant or stromal (WT1-mutant) tumours where the aggregating blastemal cells would express lower levels of FOXD1." (PMID 29040332, 2017). "Third, while in vivo experiments confirmed tumor growth inhibition, the specific contributions of NAT10/FOXD1 cascade to metastasis or microenvironmental crosstalk remain unexplored." (PMID 40999468, 2025). "This study establishes FOXD1 as a multi-functional oncoprotein in NPC, orchestrating tumor growth, cancer stemness, and angiogenesis." (PMID 40999468, 2025). "Our analysis of the GEO datasets (GSE12452 and GSE34573) indicated that FOXD1 expression was significantly higher in NPC tissues compared to non-tumor tissues, a finding consistent with observations in other tumor types." (PMID 40083705, 2025). "The top GRNs in primary tumors were TCF4, TAGLN2, FOXK1, and BHLHE41, whereas the top upregulated GRNs in recurrent tumor cells were FOXP2, FOXD1, SIX4, and HMGB1." (PMID 39711559, 2024). "NAT10, CCT3, PLEK2, HOXB7, FOXD1, SEC61G, and so on have been identified as tumor markers in HNSCC by performing TCGA HNSCC database analysis." (PMID 37679666, 2023). "FOXD1 binds to the p21 promoter and inhibit its transcription, which inhibits the CDK2/Rb signaling pathway, thus preventing tumor cell senescence and accelerating tumor cell proliferation." (PMID 37563111, 2023).
tumor (continued). "Analysis of the promoter methylation levels of the 15 DE-FOXs by UALCAN revealed downregulation of the promoter methylation levels of FOXD1, FOXJ1, and FOXK1 in tumor tissues." (PMID 36622275, 2023). "Overexpressing FOXD1 enhanced the migration capability of BC cells, CTC formation and BC metastasis, via facilitating epithelial-mesenchymal transition of tumor cells." (PMID 36229838, 2022). "All these effects can be reversed by ectopic expression of FOXD1, thus strongly supporting our notion that USP21-mediated FOXD1deubiquitination sustains MES properties of GSCs, and eventually contributes to tumor progression in GBM." (PMID 35974001, 2022). "We also evaluated the clinical benefit of blocking FOXD1’s regulatory cascade in BC, and found that ERK1/2 inhibitor effectively reduced CTC formation and tumor metastasis in BC." (PMID 36229838, 2022). "FOXD1 expression, TNM stage and tumour differentiation were proven to be independent factors for both OS and DFS through the previous analysis." (PMID 35579380, 2022). "Compared to normal samples, the expression of E2F2, FOXJ1, EMX1, PAX7, NKX6-1, FOXD1, and ZNF552 was significantly higher (P < 0.05) and the expression of MSX1, STAT4, NR3C2, and EGR3 was significantly lower in tumor samples (all P < 0.05)." (PMID 33688372, 2021). "Our results offer novel insights into the functional role of FOXD1 in HNSC, thereby highlighting a potential mechanistic basis whereby FOXD1 influences TAM infiltration and immunosuppressive gene expression in tumor microenvironment (TME)." (PMID 34028536, 2021). "Thus, we speculated that FOXD1 was a tumor promoter in HNSC." (PMID 34269372, 2021). "FOXD1, located at chromosome 5q12, is a newly discovered member of the FOX transcription factor family and acts as a tumor facilitator in various cancers." (PMID 32669972, 2020). "A number of TFs were significantly altered in two or more tumour types, including ZEB1, JUN, ELK1, FOXM1, while others were limited to a single type, such as FOXD1 in HNSC and FOXL1 in KIRC." (PMID 28139702, 2017). "For example, FOXD1 is typically expressed in stromal cells and also in all WT1 mutant tumor derived cell lines we have established previously." (PMID 27213811, 2016). "However, there still are several limitations, such as the development of brain penetrant inhibitors of UBA2, RALY, FOXD1, and DKK1 that can be selective against tumor cells as well as more studies for clinical research." (PMID 37906341, 2023). "Our data demonstrated that early CTC formation was not a random process; it was under the influence of FOXD1-dependent signaling cascade that BC cells acquired the potential for motility to detach and disseminate from primary tumor foci in BC." (PMID 36229838, 2022). "Expression levels of FOXD1, a marker for stromagenesis, were ascertained by QPCR and shown to be highest in the blastemal-predominant tumours whose histology includes few or no UB-like structures." (PMID 29040332, 2017). "Additionally, NAT10 silencing diminished tumor microvessel density (MVD) of C666-1 NPC xenografts, which could be reversed by FOXD1 reconstitution." (PMID 40999468, 2025). "Without a question, FOXD1 contributes significantly to tumor genesis and progression." (PMID 38827805, 2024). "In addition, we found that FOXD1 directly bound to the promoter of p21 and inhibited its transcription, which blocked the CDK2/Rb signaling pathway, thereby preventing the senescence of tumor cells and accelerating tumor cell proliferation." (PMID 37563111, 2023). "This suggests that although FOXD1 plays a role in tumor progression and shorter prognosis, it may not be involved in cell cycle regulation." (PMID 37234983, 2023).
tumor (continued). "In vitro experiments revealed that FOXD1 bound to the p21 promoter and inhibited its transcription, which blocked the cyclin dependent kinase 2 (CDK2)/retinoblastoma (Rb) signaling pathway, thus preventing senescence and accelerating proliferation of tumor cells." (PMID 37563111, 2023). "For example, miR-655 may suppress the proliferation of PCa cells and tumor metastasis by inhibiting TRIM24 and miR-30a may inhibit the androgen-independent growth of PCa cells by targeting the expression levels of MYBL2, FOXD1, and SOX4." (PMID 35782093, 2022). "Univariate Cox regression analysis identified TNM stage (OS: p < 0.001; DFS: p < 0.001), tumour differentiation (OS: p < 0.001; DFS: p < 0.001) and positive FOXD1 expression (OS: p = 0.033; DFS: p = 0.027) as clinicopathological factors that might stronly affect prognosis." (PMID 35579380, 2022). "The FOXD1 expressions in tumour tissues exceeded those in adjacent normal tissues significantly." (PMID 35579380, 2022). "SL exposure also induced changes in the expression of genes involved in metabolic functions in tumor and stem cells (ALDH1B1, ABCB1, SLC3A2, SLC44A2, SLC31A2, SLC7A11, CYP24A1, PTGS2/COX2, PPRC1), cytokines (CCL3L3, GDF15) and growth and differentiation factors (PGF, TGFBR11 and FOXD1)." (PMID 24742967, 2014).
cancer (37 papers, 2012 to 2025). A tumor composed of atypical neoplastic, often pleomorphic cells that invade other tissues. "Recent studies have proved that FOXD1 is associated with tumorigenesis and cancer progression, serving as a prognostic indicator and a prospective target in some sorts of cancers." (PMID 37563111, 2023). "Further analysis of GSEA, GO and KEGG showed that FOXD1 expression was significantly associated with oncological function and cancer-related pathways." (PMID 34772357, 2021). "Recent reports indicated that FOXD1 plays a oncogenic effect in several types of cancer and likely associates with the mechanism for radioresistance." (PMID 32967107, 2020). "Numerous studies have shown that FOXD1 dysregulation is linked to the development of diverse diseases, including recurrent pregnancy loss, renal fibrosis, liver fibrosis, and cancer." (PMID 41214670, 2025). "Transcription factor FOXD1 has been implicated in the development of various cancers 26-30." (PMID 40083705, 2025). "Accumulating evidence has demonstrated that FOXD1 is associated with tumorigenesis and cancer progression, such as therapeutic resistance and cancer metastasis, and serves as a prognostic biomarker and a promising target in several types of cancer." (PMID 35974001, 2022). "Recently, many studies indicated that FOXD1 was involved in the development and progression of different types of human cancers, and its dysregulation was mainly associated with cell proliferation, migration, invasion, radioresistance, and epithelial-to-mesenchymal transition (EMT)." (PMID 35607308, 2022). "Innumerable studies have reported that FOXD1 performs critical roles in common physiological functions as well as multiple disease progression, such as recurrent pregnancy loss 6, osteoarthritis 7, kidney development 8, and malignant biological progression of several cancers 9-11." (PMID 40083705, 2025). "FOXD1 has been found to be involved in several types of cancer; however, its role in mediating cancer cell growth under hypoxia conditions is unclear." (PMID 41214670, 2025). "Upregulation of FOXD1 in these clinical cancer tissues was validated by quantitative PCR and immunoblot assays compared to the matched normal counterparts." (PMID 40999468, 2025). "In oncogenesis, FOXD1 exhibits oncogenic properties across multiple cancers by modulating EMT, stemness, and therapy resistance through diverse signaling pathways." (PMID 40999468, 2025). "In NPC, FOXD1 has been shown to contribute to cancer progression and gemcitabine resistance by enhancing mitophagy." (PMID 40999468, 2025). "Particularly, FOXD1 acts as an oncogene in mediating the onset and progression of numerous human cancers." (PMID 41214670, 2025). "From this study we can use FOXD1 to predict the course of the disease and at the same time study its upper and lower pathways to find therapeutic drugs to treat the cancer." (PMID 38827805, 2024). "Individuals with elevated FOXD1 expression had poorer survival predictions and worse clinicopathological parameters in most of cancers compared with patients with low FOXD1 expression." (PMID 38827805, 2024). "In our research, we proved that FOXD1 directly bound to the p21 promoter regions and downregulated its expression, thereby inhibiting the senescence of cancer cells." (PMID 37563111, 2023). "The FOXD1 expression matrix demonstrated that FOXD1 was over-expressed in various types of cancers and corresponded to a bad survival." (PMID 37563111, 2023). "Recent reports have indicated that the abnormal overexpression of FOXD1 is related to tumorigenesis and the progression of several types of cancers." (PMID 38092733, 2023). "Our present data and previous studies indicate that the overexpression of FOXD1 is closely involved in aggressive cancer cell transformation in a wide range of cancers, including HNSCC." (PMID 35886008, 2022).
cancer (continued). "In this study, we confirmed that the overexpression of FOXD1 facilitated cancer cell malignant transformation, e.g., enhanced migratory and invasive abilities in HNSCC cells." (PMID 35886008, 2022). "The aberrant expression of FOXD1 facilitated cancer cell migration and invasion, and its expression was closely associated with the prognosis of HNSCC patients." (PMID 35886008, 2022). "FOXD1 expression has been assessed in multiple cancer types and is often correlated to a poor prognosis." (PMID 35954332, 2022). "Mounting study as well as pan-cancer analysis (downloaded from GEPIA2) have revealed that FOXD1 is overexpressed in a variety of cancers and has to do with unfavorable prognosis." (PMID 34772357, 2021). "Gene Set Enrichment Analyses (GSEAs) revealed that FOXD1 was mainly involved in cancer-related signaling pathway and metabolism-related pathways." (PMID 34269372, 2021). "Among these FOX gene regulators, FOXD1 has been increasingly recognized as a key agent for cancer initiation, unrestricted growth, and metastasis, and has been proven to be a promising therapeutic target." (PMID 34772357, 2021). "In our study, we examined the FOXD1 expression levels and prognostic function in pan-cancer using TCGA data from UCSC Xena." (PMID 34028536, 2021). "Taken together, combined with bio-informatics analysis and the results of our findings and others strongly favors the notion that FOXD1 probably functions as a hypothetical oncogene by facilitating cancer cell proliferation, migration and invasion." (PMID 34772357, 2021). "GSEA analysis revealed that differentially expressed genes between high-FOXD1 and Low-FOXD1 groups were involved significant pathways included KEGG Pathways in cancer, EMT pathway, KEGG Focal adhesion and Apoptosis." (PMID 34772357, 2021). "In the present study, we found that mRNA and protein levels of FOXD1 was up-regulated in HNSC cell lines, and FOXD1 expression was increased in cancer tissues compared with corresponding adjacent normal tissues." (PMID 34269372, 2021). "Accumulating evidence suggests that both FOXD1 and Gal-3 are highly expressed in several cancers, whereas the clinicopathological relationship is still not well understood." (PMID 31795213, 2019). "The tumorigenic role of FOXD1 has been identified; however, the oncogenic role remains controversial in various cancers." (PMID 31795213, 2019). "The expression status and roles of FOXD1 in many types of cancer have been reported." (PMID 41214670, 2025). "Since NAT10 is a well-established ac4C writer in promoting cancer progression, our study proposed that it may mechanistically regulate FOXD1 ac4C modification in NPC cells." (PMID 40999468, 2025). "Although many articles have revealed the correlation between FOXD1 expression as well as prognosis, there is presently without meta-analysis assessing the diagnostic efficacy of FOXD1 for cancers." (PMID 38827805, 2024). "High FOXD1 expression in most cancers indicates a bad prognosis and shorter survival time." (PMID 38827805, 2024). "There is also a correlation between FOXD1 and pathological parameters of some cancers." (PMID 38827805, 2024). "FOXD1 plays a role in both normal development and cancer progression." (PMID 37234983, 2023). "In addition, the present study indicated for the first time that FOXD1 has vital impact on regulating the senescence of cancer cells." (PMID 37563111, 2023). "Although FOXD1-KD downregulated cancer-associated enhancer–gene pairs, we did not observe any effect on the proliferation of either of the cell lines." (PMID 37234983, 2023). "Moreover, it has been suggested that FOXD1 plays critical roles in cell proliferation, invasion, metastasis, and poor prognosis in various cancer types." (PMID 37234983, 2023). "FOXD1 expression is upregulated in several types of cancers." (PMID 35886008, 2022).